SETX (senataxin)
Diseases named in the same sentence as SETX in open-access papers (continued):
Sharing a sentence is not in itself a finding about the gene and the disease.
ovarian carcinoma (2 papers, 2023 to 2024). A malignant neoplasm originating from the surface ovarian epithelium. "Intriguingly, BRCA1 deficiency has also been linked to POA and SETX deletion has been observed in ovarian cancers with a similar extent than BRCA1 deletions." (PMID 37147318, 2023). "Coherently with the role of EXO1 in promoting cGAS positive MN in a SETX deficient background, we found that in ovarian cancer, head and neck squamous cell carcinoma and glioma the concurrent presence of low SETX and high EXO1 expression levels leads to poor survival." (PMID 39120648, 2024). "Senataxin cooperates with the breast and ovarian cancer BRCA1 protein in the removal of R-loop-driven DNA damage at transcribed genes and was found down-regulated in a range of cancer types, including ovarian cancer, suggesting a tumor suppressor activity." (PMID 39120648, 2024). "For instances, SETX expression is downregulated in ovary carcinoma, lymphomas, primary Basal Cell Carcinoma (BCC) and Squamous Cell Carcinoma (cSCC) arising from different anatomical sites such as skin, cervical and lung." (PMID 37147318, 2023). "In ovarian cancer (OV), head and neck squamous (HNSC) cell carcinoma and low-grade glioma (LGG), low levels of SETX expression did not correlate with a poorer prognosis in the tested cohorts." (PMID 39120648, 2024).
Parkinson disease (2 papers, 2016 to 2022). A progressive degenerative disorder of the central nervous system characterized by loss of dopamine producing neurons in the substantia nigra and the presence of Lewy bodies in the substantia nigra and locus coeruleus. "We observed up-regulation of genes that were implicated in Alzheimer’s and Parkinson’s disease, respectively, and predicted to be downstream targets of SETX." (PMID 36271102, 2022). "In particular, our results suggest that transcription target genes assigned to SETX and E2F may represent important regulatory mediators that connect energy metabolism, autophagy and cellular stress with Alzheimer’s and Parkinson’s diseases." (PMID 36271102, 2022).
premature ovarian failure (2 papers, 2015 to 2022). "This may suggest an association between SETX mutations and premature ovarian failure/premature menopause that deserves further studies." (PMID 25927548, 2015). "Several previous studies have revealed that SETX may be related to hypogonadism, spermatogenesis and premature ovarian failure." (PMID 36438189, 2022).
Tremor (2 papers, 2015 to 2022). An unintentional, oscillating to-and-fro muscle movement about a joint axis. "Finally, the SETX gene is related to the tremor, which is considered a sign of PD80." (PMID 35705654, 2022).
viral infection (2 papers, 2022 to 2023). "SETX is indeed able to attenuate the transcription of IRF3-dependent antiviral genes during the early phase of viral infection." (PMID 37147318, 2023). "Furthermore, during viral infection, SETX together with the transcriptional cofactor TAF4 promotes promoter-proximal termination of the transcription of antiviral genes, attenuating thus the antiviral response." (PMID 37147318, 2023). "Notably, SETX and IRF3-dependent signaling are also interconnected during virus infection." (PMID 37147318, 2023).
apraxia (1 paper, 2022). Apraxia is a neurological disorder characterized by the inability to perform tasks or movements, despite having the desire and physical ability to perform them. "Additionally, recessive mutations in Senataxin (SETX), an RNA-DNA helicase, have been linked to apraxia with oculomotor ataxia type 2 (AOA2), whereas dominant mutations in the gene have been detected in a juvenile-onset form of ALS." (PMID 35456958, 2022).
Autoimmunity (1 paper, 2023). The occurrence of an immune reaction against the organism's own cells or tissues. "However, although autoimmunity is unlikely to occur for most ALS cases, it has been evoked as a possibility in certain mutation carriers such as those with alterations in C9ORF72 and senataxin (SETX) genes." (PMID 37371694, 2023).
B-cell lymphoma (1 paper, 2020). "The BSCL2 and SETX VUS variants have been previously reported in B-cell lymphoma and cancer patients, respectively." (PMID 32397312, 2020).
Cerebellar hypoplasia (1 paper, 2023). Cerebellar hypoplasia is a descriptive term implying a cerebellum with a reduced volume, but a normal shape and is stable over time. "Seven probands carry causative variants in well-known genes associated with CA or cerebellar hypoplasia: SETX, CACNA1G, CACNA1A, CLN6, CPLANE1, and TBCD." (PMID 38003592, 2023).
cerebral malaria (1 paper, 2021). A sequestration of Plasmodium falciparum in the brain, which can cause coma and/or seizures. "Similarly, the K-TSPs model for cerebral malaria identified nine gene pairs including: TTC17-C18orf8, PUM2-ASB7, RABEP1-MYH11, SETX-SPATS2L, XRCC5-TRIP12, ELF2-CHRNA10, LARP4-ANK2, MREG-KPNA6, and ZNF197-CD53." (PMID 34746025, 2021).
cervical dystonia (1 paper, 2018). "In this context, cosegregating variants in CIZ1 and SETX were linked to cervical dystonia in a large American pedigree." (PMID 29770609, 2018).
distal myopathy (1 paper, 2021). Distal myopathy refers to a group of muscle diseases which share the clinical pattern of predominant weakness and atrophy beginning in the feet and/or hands. "Other allelic neurological disorders with the same gene associations are ataxia with oculomotor apraxia (SETX), HSP (ALS2, SPG11, ERLIN1, and DDHD1), JPLS (ALS2), dHMN (SIGMAR1), distal myopathy (GNE), and distal SMA (BICD2)." (PMID 34946884, 2021).
dysautonomia (1 paper, 2023). An acute or chronic disorder, affecting the sympathetic or parasympathetic nervous system. "Moreover, juvenile ALS due to genetic mutations in SETX and SPTLC1 seems to be associated with an increased propensity to develop sensory neuropathies and dysautonomia." (PMID 37610446, 2023).
Hypertension (1 paper, 2014). The presence of chronic increased pressure in the systemic arterial system. "However, the function of SETX and its role in hypertension remains unclear and may be worthy of further investigation." (PMID 25519331, 2014). "The function of SETX in hypertension may be worthy of further investigation." (PMID 25519331, 2014).
migraine (1 paper, 2025). "Burden testing identified several genes, including GCOM1, SETX, and SLC38A10, as significantly associated with HM, many of which have known roles in neurological function or migraine-related pathways." (PMID 40725463, 2025).
osteosarcoma (1 paper, 2025). A usually aggressive malignant bone-forming mesenchymal neoplasm, predominantly affecting adolescents and young adults. "To evaluate the role of Senataxin (SETX) in Myc-induced replicative stress (RS), we took advantage of the human osteosarcoma-derived U2OS-MycER cell line, which constitutively expresses the MycER transgene, encoding the Myc protein fused to the estrogen receptor (ER)." (PMID 40108134, 2025).
pancreatic cancers (1 paper, 2022). "Genomic analyses of pancreatic cancer patient samples reveal that expression levels of SETX and BLM correlate with the occurrence of mutational signatures previously associated to BIR." (PMID 35440629, 2022).
squamous cell carcinoma (1 paper, 2023). A carcinoma arising from squamous epithelial cells. "Remarkably, SETX expression is significantly decreased, or its gene mutated in Squamous Cell Carcinomas of different origins, which are commonly characterized by dysregulation of the differentiation program." (PMID 37147318, 2023).
neurological diseases (19 papers, 2013 to 2025). "The pathogenesis of ALS4 is still unclear, but studies have shown that it is a neurological disease caused by mutations in the SETX gene." (PMID 38678239, 2024). "The most compelling evidence of how dysfunctions of R-loops processing enzymes are linked to human health is represented by the RNA/DNA helicase Senataxin (SETX), whose mutations underlines the pathogenesis of two distinct neurological disorders." (PMID 37147318, 2023). "The type of mutations associated with these neurological diseases supports the concept that SETX loss of function underlines the pathogenesis of AOA2, while SETX gain of function is responsible for ASL4." (PMID 37147318, 2023). "Pathogenic variants of SETX cause two neurological diseases, AOA2, an autosomal recessive disorder, and ALS4, an autosomal dominant motor neuron disorder." (PMID 36438189, 2022). "SEN1 is an ortholog of human SETX (senataxin), which has been implicated in neurological disorders like AOA and ALS." (PMID 23741394, 2013). "The key importance of SETX in R-loops homeostasis and its relevance with pathophysiological events is highlighted by the evidence that gain or loss of function SETX mutations underlie the pathogenesis of two distinct neurological disorders." (PMID 37147318, 2023). "Based on the variability in neurological disease profile produced by different SETX mutations in humans, it may well be that only a fraction of mutations results in POA." (PMID 33995483, 2021). "Importantly, SETX is a gene mutated in two severe neurological diseases, AOA2 and ALS4, associated with progressive neurodegeneration." (PMID 29416069, 2018). "Indeed, different SETX mutations cause up to four distinct neurological disorders." (PMID 33995483, 2021). "ZPR1 is known to bind R-loops and SETX to recruit this helicase to these structures, although much of this work has been described in the context of neurological disease." (PMID 41305523, 2025). "In this review, we shed light on the multifaceted role of SETX in cellular processes, its role in the pathogenesis of neurological disorders and its therapeutic implication as a potential modifier of disease phenotype." (PMID 39070547, 2024). "This RNA helicase is homologous to human senataxin (SETX), a critical gene linked to neurological disorders and involved in transcription termination and R-loops regulation." (PMID 37222282, 2023). "As rare private gene variation is often difficult to link to genetic neurological disease by DNA sequence alone, we used transcriptional network analysis to functionally validate these patients with severe de novo SETX-related neurodegenerative disorder." (PMID 34922620, 2021). "Similarly, the extent to which SETX's R-loop resolving activity contributes to neurological diseases remains to be clarified." (PMID 40271193, 2025). "Furthermore, mutation of SETX also causes ataxia with oculomotor apraxia 2 (AOA-2), which is also a neurological disease." (PMID 38678239, 2024). "The role of SETX may also be examined in other cellular processes correlated with neurological disorders, such as autophagy and mitochondrial dysfunction that are associated with the pathogenesis of Alzheimer's disease and Parkinson's disease." (PMID 39070547, 2024). "In addition to neurological diseases, SETX dysregulation has been also observed in human tumors and several evidence pointed towards a tumor suppressive role of this helicase." (PMID 37147318, 2023). "In summary, we employed a genetic screen and took advantage of a cellular adaptation model to define a ubiquitination-dependent mechanism for R-loop regulation by SETX, which is controlled by the opposing activities of USP11 and KEAP1 with broad applications for cancer and neurological disease." (PMID 34526504, 2021).
cancer (15 papers, 2015 to 2025). A tumor composed of atypical neoplastic, often pleomorphic cells that invade other tissues. "Further research is needed to determine how exploiting the vulnerability associated with SETX loss-of-function can be leveraged to enhance the efficacy of cytotoxic therapies targeting Myc-driven cancers." (PMID 40108134, 2025). "While our study and others have implicated SETX as a key factor in supporting cancer cell fitness, suggesting its potential as a therapeutic target, it’s crucial to acknowledge the evidence that SETX can also act as a tumor suppressor in specific contexts." (PMID 40108134, 2025). "Senataxin is an evolutionarily conserved DNA/RNA helicase, whose dysfunctions are linked to neurodegeneration and cancer." (PMID 39120648, 2024). "Here, we show that FANCD2 is necessary to counteract endogenous RS and allow proliferation of SETX-deficient cancer cells." (PMID 36543851, 2022). "This also suggests that endogenous stress in SETX-depleted cancer cells likely reflects transcription-associated RS resulting in R-loops." (PMID 36543851, 2022). "Furthermore, a pan-cancer analysis of the TCGA data revealed that while Myc amplification is associated with poor prognosis, the presence of SETX missense mutations is linked to improved outcomes in Myc-amplified tumors." (PMID 40108134, 2025). "This is particularly relevant since alterations of EXO1 expression could enhance and uncover a neglected detrimental effect of SETX deficiency in cancer." (PMID 39120648, 2024). "To this aim, we will describe the functional relevance of SETX in regulating gene expression, genome integrity, and inflammation response and discuss how cancer-associated SETX mutations might affect these pathways, contributing thus to tumor development." (PMID 37147318, 2023). "Taken together, these results show that SETX and FA proteins act upon similar structures that form as a consequence of TRCs where they can back each other up to sustain endogenous transcription-associated RS in cancer cells." (PMID 36543851, 2022). "To this aim, in the next paragraphs we will describe the functional relevance of SETX in gene expression, genome integrity and inflammation response and discuss how cancer associated SETX mutations might contribute to the pathogenesis of human cancer." (PMID 37147318, 2023). "Our findings highlight the requirement for efficient R-loop resolution by SETX at genes prone to undergo TRCs at the early stages of DNA replication and indicate that SETX is a potential therapeutic target in cancer." (PMID 40108134, 2025). "This possibility is of particular interest since Senataxin protein is reduced in a subset of cancer types and the relationship between inflammation and cancer development, progression and therapy is of great relevance, although multifaceted." (PMID 39120648, 2024). "Particularly, in cancer cell lines, MN are detectable in the cytoplasm of up to 11% of SETX depleted cells and of up to 4% of siCTRL transfected cells." (PMID 39120648, 2024). "In accordance with previous observations in other human cell lines, we found that cancer cells depleted of Senataxin activate interferon I and interferon-stimulated genes transcription in a cGAS-dependent manner." (PMID 39120648, 2024). "SETX has been identified in a screen for tumor suppressor genes and its expression is markedly downregulated in diverse human cancer types." (PMID 37147318, 2023). "A relevant example of such functional interactions is represented by the ability of SETX to interact with BRCA1, a tumor-suppressor gene mutated in breast, ovarian and other types of cancers." (PMID 37147318, 2023). "Since there is little research on the role of ZNF560 and SETX in cancers, more researches are needed to understand their roles in LUAD." (PMID 30419062, 2018).
cancer (continued). "Paradoxically, inhibiting a helicase like DDX or SETX in such a cancer could create an unmanageable level of R-loops, specifically killing the cancer cells, while normal cells with intact pathways handle it." (PMID 40332372, 2025). "Here, we report that Senataxin deficiency induces the formation of MN in cancer cells, in the absence of any other stress condition." (PMID 39120648, 2024). "To further establish whether the interplay between SETX and POLD3/BLM impacts genome stability, we examined genomic signatures in cancer databases with relation to SETX, POLD3 and BLM expression." (PMID 35440629, 2022). "Thus, the study of R-loop-dependent dysfunctions in Senataxin-deficient cells is paradigmatic for our understanding of the negative impact of these structures in both cancer and neurodegeneration." (PMID 39120648, 2024). "Collectively, our data demonstrate that continuous cycling of SETX-deficient cells relies on FANCD2-mediated rescue of endogenous RS and chromosome under-replication during mitosis, underscoring the possibility to exploit a novel synthetic proliferation defect for cancer therapy." (PMID 36543851, 2022). "Therefore, we uncovered a synthetic lethality between SETX and FA proteins for tolerance of transcription-mediated RS that may be exploited for cancer therapy." (PMID 36543851, 2022). "Though further work will be necessary, we anticipate that the synthetic lethal interaction we uncovered between SETX and FA proteins may direct new strategies for cancer treatment, with similar therapeutic applications as the successful use of PARP inhibitors in BRCA-mutant tumors." (PMID 36543851, 2022). "To assess whether our findings about Senataxin and EXO1 roles in cGAS positive MN production could influence the pathogenesis of human cancer, we studied the expression of these two proteins in different publicly available data sets in the TCGA repository." (PMID 39120648, 2024). "Although the role of SETX in cancer has not been known, its expression level is relatively lower than other genes." (PMID 30419062, 2018). "However, the relevance of SETX function in cancer cells that sustain intrinsic RS47 has not been fully established." (PMID 36543851, 2022). "Importantly, co-depleting FANCD2 together with SETX impairs cancer cell proliferation, without significantly affecting non-cancerous cells." (PMID 36543851, 2022).